RN7SKP283 (RN7SK pseudogene 283)
Gene: Miscellaneous RNA gene on chromosome 2 (229,236,340 to 229,236,609, reverse strand). Ensembl gene ENSG00000253006.
Homologues: Orthologues: guinea pig 7SK (43% identical), guinea pig 7SK (42% identical), mouse Gm54723 (31% identical). Paralogues in human: RN7SKP33 (54% identical), RN7SKP9 (54% identical), RN7SKP133 (54% identical), RN7SKP217 (54% identical), RN7SKP72 (54% identical), RN7SKP214 (53% identical), RN7SKP124 (53% identical), RN7SKP203 (53% identical), RN7SKP107 (53% identical), RN7SKP198 (53% identical), RN7SKP204 (53% identical), RN7SKP225 (53% identical), and 284 more.